IL10 (interleukin 10)
Diseases named in the same sentence as IL10 in open-access papers (continued):
Sharing a sentence is not in itself a finding about the gene and the disease.
infection (continued). "The infection was accompanied by increased production of IL-4 and IL-10, and the reduction in IFN-γ and IL-17, cytokines crucial for the induction and progression of EAE." (PMID 26114122, 2015). "These opposing effects of IL-10 and miR-155 on humoral response led to an assessment of the contribution of these regulators to antibody production during infection with B. burgdorferi." (PMID 26252010, 2015). "It is possible that the resistin-mediated effects on proinflammatory cytokines operate independently of regulatory mechanisms such as regulatory T cells and IL-10 that also contribute to chronicity of infection." (PMID 25568944, 2015). "As infection progresses to late stages (week 8 p.i.), infected untreated mice showed elevated levels of IL-10 in plasma, indicative of Treg and Th2 responses." (PMID 26191954, 2015). "While IL-10 expression levels were highest on day 3 post-infection other chemokines and cytokines had maximal expression at later timepoints (e.g. TGF-β on day 4; IL-8, RANTES and MCP-1α on day 6 and IFN-γ on day 8)." (PMID 26641081, 2015). "Taken together, these studies show that helminths can induce Breg cells that can protect against allergic diseases via the release of IL-10 and that this process is particularly active during the chronic stage of infection." (PMID 26236565, 2015). "With progress of infection, immune response was constantly enhanced and expression of IL-10 began to increase at 8 h to suppress Th1 inflammation response in order to avoid excessive tissue damage." (PMID 26427623, 2015). "EDLF at the early stages p.i. drastically inhibited the infection-induced IL-2 generation, while upregulated IL-10, which inhibits Th1 inflammatory response." (PMID 26191954, 2015). "Th1 cells are the major source of IL-10 during this infection, as in other chronic parasitic infections, and it is induced by IL-27." (PMID 26646149, 2015). "Enrichment of certain phenotypes such as CD103+CD11b-IL10+ dendritic cells during infection bestows protective systemic immunity in H. pylori-colonized hosts." (PMID 26367386, 2015). "For that, we injected intravenously C57BL/6 mice with stationary promastigotes of each L. infantum strain and analyzed the liver expression of Nos2 and Arg1 as well as of Tnf, Ifng, Il-12p40 and Il-10 genes, 15 and 60 days after infection." (PMID 26684322, 2015). "The analysis revealed that IL-10 at 6 h, CRP at 6 h and NIHSS on admission are independently associated with infection (IL-10: P = 0.009; CRP: P = 0.018; NIHSS: P = 0.041)." (PMID 25613713, 2015). "Cells from diabetics produced higher levels of IL-4 and of both, IL-4 and IL-10 as well as granulocyte-macrophage colony-stimulating factor (GM-CSF) on the first and third day post-infection, respectively." (PMID 25909658, 2015). "In the IL-10 treatment groups, mice were given 4μg recombinant murine IL-10 daily from day 17 post-infection." (PMID 26505761, 2015). "In contrast, IL-10 levels were significantly increased during infection in AM and MM groups (p = 0.03 and p < 0.001, respectively)." (PMID 25889717, 2015). "IL-10, a cytokine with anti-inflammatory properties, has a central role in infection by limiting the immune response to pathogens and thereby preventing damage to the host reducing excessive immunopathology caused by inflammatory cytokines." (PMID 26193305, 2015). "The increased expression of TLR2 and TLR4 by the Treg cells results in increased IL-10 which can play an immunotolerogenic role during the infection." (PMID 26635448, 2015). "Next we evaluated the possible immunomodulatory role of IL-10 in the infection of B-1CDP cells in comparison with peritoneal macrophages." (PMID 25933287, 2015). "It has been demonstrated that, in the absence of Th1 cells, infected mice produce large quantities of IL-10 and readily succumb to infection with attenuated aroA−aroD−S." (PMID 26441965, 2015).
infection (continued). "We developed and employed two different mathematical models to explain the MAP experimental infection data (IL-10, IFN-γ (Th1), IL-4 (Th2), and CFU (bacteria)) from calves that were followed over a period of 360 days in the study." (PMID 26619346, 2015). "In contrast, levels of IL-10 increased significantly at 72 hours post-infection in drug treated animals." (PMID 26381144, 2015). "Similar to vaginal tissues, uterine samples collected 35 days post-infection with C. trachomatis had increased expression of Il10 and TNF." (PMID 26779389, 2015). "In agreement with the literature, we noticed an increase in IL-10 mRNA levels in the Cre- group during the first 2 weeks of infection." (PMID 26046638, 2015). "Upon peroral infection A. butzleri stably colonized the intestinal tract of gnotobiotic IL-10−/− mice." (PMID 26483849, 2015). "There was no increase in the percentage of CD4+ Foxp3+ Treg cells expressing IL-10 upon infection in either the tLN or spleen." (PMID 26195548, 2015). "Repeated albendazole treatments have a significant effect in the way children respond to immune stimulus, and an immune modulatory effect by IL-10 is likely more evident in chronic or high-intensity infections." (PMID 25888883, 2015). "In patients with infection, levels remained elevated until 24 h in the case of IL-10 and until day 7 in the case of IL-6 and CRP, respectively." (PMID 25613713, 2015). "Serum levels of the pro-inflammatory cytokines IL-1ß, IL-6, IL-12, and TNF-α and the anti-inflammatory IL-10 appeared similar in anesthetized and Intralipid control animals during the first 48 hours post-infection." (PMID 26381144, 2015). "At 30 h post infection, IL-10 and KC levels were lower in C/EBPδ−/− brain homogenates, whereas brain IL-6, TNF-α, IL-1β, and MIP-2 levels were not significantly different between the two genotypes." (PMID 25958220, 2015). "For example, a surge in IL-10 in serum often follows release of pro-inflammatory cytokines such IFN-γ during an infection; in such cases the surge in IL-10 production is a consequence of inflammation rather than a contributor to it." (PMID 26566996, 2015). "Although myeloid cells can contribute to IL-10 production, it appears that T cells are the major source of IL-10 in a variety of infections." (PMID 26417443, 2015). "It is important to note that IL-33-treated mice produced minimal amount of IL-10 during PbA-infection." (PMID 25659095, 2015). "If the IL-10 somehow acts as a weapon used by the bacilli to interfere with proper macrophage activation during active infection, participation in controlling exacerbation of the immune response seems to be of vital importance to the infected individual." (PMID 26495323, 2015). "Both infection and the production of IL-10 were decreased when PGE2 production was blocked by NSAIDs." (PMID 25933287, 2015). "Neither pentoxifylline alone or in combination with anti-leishmanial drugs affected the secretion of IL-10 induced by infection." (PMID 26024228, 2015). "IL-10 release was greater (P<0.05) on day 1, remained stable during the first 3 days of infection and was higher on day 3 in the pAOS group compared with the control group." (PMID 26599638, 2015). "The PABPs specific IgG2a/IgG1 and IFN-γ IL-10 ratios were reverted in the LiPABP vaccinated and protected mice, in comparison to mice from both control groups after infection." (PMID 25955652, 2015). "The highest number of IL-21-producing CD4+ T cells co-expressing IFN-γ and IL-10 was detected at day 15 post-infection." (PMID 25763578, 2015). "In context to the slight but insignificant reduction of IL-10 level after NGAL stimulation, macrophages obtained from NGAL deficient mice displayed a significant increase of IL-10 levels during infection with Chlamydia pneumoniae." (PMID 25893429, 2015).
infection (continued). "Our team recently identified a novel subset of CD11b+F4/80hiCD64+CX3CR1+ MNPs that expand upon infection, secrete high levels of IL-10 and are required for maintaining elevated levels of H. pylori in the stomach mucosa early during infection." (PMID 26367386, 2015). "Of note, the multivariate analysis revealed an independent association of IL-10 and CRP with infections, suggesting a strong effect of the inflammatory and anti-inflammatory reaction on the development of infections." (PMID 25613713, 2015). "In cultured MØs, ultraviolet irradiation of RV1B abrogated the eotaxin, IL-10, and IFN responses, indicating that RV causes a replicative infection in MØs, and cytokine expression is dependent on viral replication." (PMID 25430775, 2015). "On the other hand, IL-10 plays a regulatory role in dampening the excessive proinflammatory cytokines produced during infection." (PMID 25875604, 2015). "Fifty-five days after infection, the serum levels of IL-10 were statistically significantly higher in the infected TTR-NP mice than in the B6 mice and remained elevated up to 147 days after infection." (PMID 28210682, 2015). "Together, our data suggest that IL-10 released at the site of infection strongly contributes to exacerbative activity of nucleosides during Leishmania infection." (PMID 25849562, 2015). "The immunosuppressive activity of IL-10 is required for maintaining healthy immunity during infection, and has pleiotropic effects on many inflammatory mediators, notably through suppressing a number of innate and adaptive cytokines including IFNγ." (PMID 26252010, 2015). "The up-regulated expression of IL-4, IL-5, IL-10, and IL-13 showed Th2 cell predominance in immunopathological reactions at late infection phase in response to infection by A. cantonensis." (PMID 26070790, 2015). "The lungs of ECTV-infected Fas- and FasL-deficient mice showed significant inflammation during later phases of infection accompanied by decreased expression of anti-inflammatory IL-10 and TGF-β1 cytokines and disturbances in CXCL1 and CXCL9 expression." (PMID 25873756, 2015). "Th2 cytokines, IL-4 and IL-10, are elevated starting approximately 2 weeks after infection and peak at three weeks following infection during the resolution stage." (PMID 26697208, 2015). "The more prominent transcript levels of IL-10 in the gastric lymph node of naïve 5-month-old lambs following infection with T. circumcincta, when compared with previously infected lambs, is consistent with the findings in yearling sheep." (PMID 24712712, 2014). "We therefore performed a genome-wide screen of changes in miRNA expression in joints of B6, C3H and B6 IL-10−/− mice infected with B. burgdorferi at one and two weeks post-infection using an Agilent mouse microRNA microarray." (PMID 24967703, 2014). "The infection of mice overexpressing IL-10, which mimics tuberculosis reactivation, reveals features of M2 macrophages in C. burnetii infection of mice." (PMID 25346736, 2014). "Levels of CXCL1/KC, IFN-γ, TNF-α, and IL-10 in the lung 1, 7, 15 and 30 days post-infection were significantly higher (approximately 30%, 40%, 19% and 36%, respectively) (p<0.05) in mice infected with the L27/01 strain, particularly 1 to 7 days post-infection." (PMID 25392951, 2014). "In fact, we did observe significant decrease in the percentage of IL17-secreting CD3+CD4+CD25− T cells and a significant increase in splenocyte secretion of IL-10, a cytokine secreted by Treg cells, following infection with BCG-TB1860, compared to BCG-GFP." (PMID 24945624, 2014). "We found that saliva does indeed enhance infection levels of vector-transmitted pathogens and leishmaniasis pathology in naïve mice and elevates Th2 cytokine levels (IL-4 and IL-10)." (PMID 25275509, 2014). "The systemic IL-10/IL-12 axis was skewed after burn injury and infection demonstrated by a substantial elevation in serum IL-10." (PMID 24454904, 2014).
infection (continued). "The splenocytes of infected/WT mice exhibited a predominance of TNF-α (TNF-α>IL-10>IFN-γ) release throughout the course of infection." (PMID 25474113, 2014). "During Leishmania, T. cruzi and T. gondii infection polarized Th1 cells produce IL-10 along to IFN-γ, in attempt to control immunopathology." (PMID 25233271, 2014). "B6 and IL-10−/− mice exhibited a >1 log increase in IFN-γ expression over uninfected FP throughout infection." (PMID 25210773, 2014). "Other studies using il10 knockout mice showed that these animals have a more efficient control over the infection by T. cruzi, reducing parasitism levels with a significant increase in the secretion of IFN-γ, TNF-α, IL-12, and NO." (PMID 25050370, 2014). "The anti-inflammatory mediator IL-10 started to increase at 6 h post infection for all stimuli, but showed different kinetics for low dose C. pneumoniae and LPS." (PMID 25488836, 2014). "When we compared the ratio of IFN-γ to IL-10 secreting cells in the PBMC of immunized macaques, there was a significant increase in the IL-10 secreting cells in the two vaccinated macaques that showed infection." (PMID 25401783, 2014). "Earlier studies from our group have shown that SbR-LD infection generates more IL-10 from both macrophages and dendritic cells." (PMID 25032977, 2014). "IL-10 levels were significantly elevated at the earliest times of infection in pediatric patients who died." (PMID 25279581, 2014). "Parasite numbers were counted in blood and skeletal muscle at different times post-infection, and real time-PCR expression levels of the cytokines IL-12, IL-4, IL-10, IFN-γ, and TNF-α were evaluated." (PMID 24991553, 2014). "Administration of the anti-inflammatory cytokine IL-10 can attenuate FGR induced in rats by lipopolysaccharide (LPS) or infection with E. coli." (PMID 24904596, 2014). "As in Mif−/− mice, the pro-inflammatory cytokine production was decreased and IL-10 production was elevated during the chronic stage of infection upon anti-MIF IgG treatment of WT mice." (PMID 25255103, 2014). "Blocking of TLR4 prior to infection increased IL-10 secretion compared to unblocked infection (p = 0.0399)." (PMID 24489729, 2014). "Total splenocytes were then harvested on day 7 after infection (day 3 post-transfer), and IL-10 production by donor OTII and recipient T cells (distinguished based on CD90, CD4, CD8 and CD45.1/2 expression) was measured." (PMID 24613988, 2014). "Our score system, based on the most characterized M1 and M2 markers (TNFα and IL10, respectively), showed that MΦs from all patients suffering from a subsequent infection exhibited an evident M2 phenotype." (PMID 24797663, 2014). "Saliva was demonstrated to enhance pathology, infection level, and the production of Th2 cytokines (IL-4 and IL-10) in naïve mice." (PMID 25275509, 2014). "Molecular analyses revealed an increased expression of the immune inhibitory cytokine interleukin-10 in DCs following infection." (PMID 24769532, 2014). "Other studies demonstrated that the protective efficacy of vaccine antigens not only depends on the amount of IFN-γ but also IL-10 at the time of challenge infection." (PMID 25500571, 2014). "The systemic IL-10/IL-12 axis was skewed after burn injury with infection as indicated by a significant elevation in serum IL-10 and polarization of neutrophils into an anti-inflammatory (“N2”; IL-10+ IL-12−) phenotype." (PMID 24454904, 2014). "In vitro infection of murine macrophages and dendritic cells with Pentavalent antimonial resistant (SbR) LD isolates also triggers greater production of IL-10, compared to that of Pentavalent antimonial sensitive (SbS) LD infection." (PMID 25032977, 2014). "IL-10 is also induced during infection with another intracellular bacteria, Listeria monocytogenes, where type I IFNs are similarly detrimental to the host." (PMID 25187652, 2014).
infection (continued). "There were 9 to10-fold reductions in IL-10, for rCPC and cocktail immunized groups (p<0.0001) after 3 months post infection compared to adjuvant controls which was directly related to disease progression." (PMID 25144181, 2014). "IFN-γ and IL-10 are two cytokines that have antagonistic effects on macrophages: IFN-γ stimulates macrophage activity in the presence of infection, whereas IL-10 has inhibitory effects." (PMID 25118595, 2014). "It was reported that IL-10 given at latter stages of infection prevented severe inflammation and lung edema and facilitated bacterial clearance in mice treated with ceftriaxone." (PMID 24565171, 2014). "Lower levels of IFN-γ were detected at week 2 of infection in both mouse strains treated with 1MT, but IL-12, IL-4 and IL-10 appeared in lower levels only in B10.A treated mice." (PMID 25411790, 2014). "IL-4, IL-10 and IL-12a expression in the thymocytes of LPi mice were almost undetectable due to an interaction of low protein diet and infection, whereas TGF-β was increased due only to the effect of low protein diet." (PMID 25535967, 2014). "We observed that the lower IL-10 levels assessed during the acute and post-acute phases of infection in MHC class II M3 haplotype animals were concomitant with the lower α-defensin values associated with MHC class IA M3 in acute infection." (PMID 24695530, 2014). "While both direct infection and exposure of CD8αneg DCs were found to contribute to elevated IL-10, different modes for each subset were identified." (PMID 24613988, 2014). "In summary, infection following burn injury led to a predominant systemic IL-10 response, while infection after sham treatment induced an IL-12 response." (PMID 24454904, 2014). "This IL-10 secretion was shown to be mediated by phagocytosis of opsonized parasites in an in vivo model of low dose infection with L. major and also with L. amazonensis and L. mexicana." (PMID 25368612, 2014). "Conversely, serum IL-10 levels progressively increased during the chronic stage of infection (day 18 p.i. till the end) in Mif−/− mice whereas they were low/marginal in WT mice." (PMID 25255103, 2014). "Epstein-Barr virus (EBV) encodes an IL-10 homologue (vIL-10) expressed during productive (lytic) infection and induces expression of cellular IL-10 (cIL-10) during latency." (PMID 25324959, 2014). "As an immediate interaction response, at early time points several immune cells including monocyte/macrophage, CD4+CD25−CD127− Tr1 and CD4+CD25+CD127low/− iTreg cells produce IL-10 in both SbS and SbR-LD infection." (PMID 25032977, 2014). "On the other hand, the high dose group (109 CFU/mouse), showed significant release of IFN-γ (p = 0.03), IL-2 (p = 0.02), and IL-10 (p = 0.01) in harvested spleenocytes stimulated with Johnin compared to media only controls by 12 weeks post infection." (PMID 24551602, 2014). "The results are consistent with a role for IL-10 in modulating iron metabolism during acute phase of infection." (PMID 24520384, 2014). "Th-1 cytokines such as IFN-γ, TNF-α, and IL-2 favor resistance to infection while IL-4, IL-10 and IL-13 mediate disease progression and parasite persistence." (PMID 25500571, 2014). "We showed that the infection significantly suppressed OVA-induced eosinophilic airway inflammation through enhancing the level of IL-10 and down-regulation of IL-17A." (PMID 25409540, 2014). "Yet, absence of MIF slightly increased survival time and reduced serum IFN-γ, TNF, and IL-6 concentrations while inducing IL-10 production in the chronic stage of infection." (PMID 25255103, 2014). "Less IL-1β and KC were found at 3 hours for the resistant mice (S/C-KO), as well as less IL-10 both at 1.5 and 3 hours post-infection." (PMID 24498223, 2014). "In bovine intestinal tissues early post-infection, MAP induces anti-inflammatory genes such as IL-10 associated with increased intracellular survival." (PMID 25480162, 2014).